CD4 (CD4 molecule)
Diseases named in the same sentence as CD4 in open-access papers (continued):
Sharing a sentence is not in itself a finding about the gene and the disease.
hepatotoxicity (11 papers, 2010 to 2022). Toxicity that causes injury to the liver or impairs the liver function. "Our study also found the baseline CD4 counts and the development of rashes were associated with hepatotoxicity among the patients starting NVP-containing regimens." (PMID 28222098, 2017). "The relatively higher mortality in week one is partly explained by increased proportion of cases with CD4 counts < 50cells/μL, which is independent risk factor for mortality as well as grade 3 and 4 hepatotoxicity." (PMID 25966339, 2015). "Liver toxicity associated with nevirapine is supposed to occur more frequently in the first 18 weeks of treatment, and in our study grade ≥ 2 early toxicity occurred almost exclusively among women with baseline CD4+ count > 250/mm3." (PMID 24708626, 2014). "Thus, we estimated in the MTCT-Plus program in Abidjan, Côte d'Ivoire, the incidence rate of all severe adverse events (SAEs) according to CD4 cell count and pregnancy status, especially hepatotoxicity and/or rash and investigated their risk factors in women initiating NVP-based HAART." (PMID 20576111, 2010). "Seven women developed severe liver toxicity (grade 3 or 4) (2.25%) : 5/147 (3.4%) women with baseline CD4+ < 350/mm3 vs 2/164 (1.2%) women with baseline CD4+ > 350/mm3(P = 0.26)." (PMID 23894379, 2013). "Among participants who initially received NVP,grade 3 or 4 hepatotoxicity occurred in 9 of 196 (5%) women with abaseline CD4 count of ≥250 cells/mm3 versus three of 114(3%) women with CD4 count of <250 cells/mm3(RR = 1.7, 95% CI 0.5–6.3)." (PMID 21468300, 2011). "One study conducted in Mozambique among 146 pregnant women found a higher rate of severe hepatotoxicity in women with CD4 >250 cells/mm3 (6.0% vs 0.0%; p = 0.02)." (PMID 20576111, 2010). "Overall, nevirapine-associated toxicity (including grade 3 or 4 events and assuming that all liver toxicity was related to nevirapine) occurred in 22/311 women (7.1%) (10.2% with baseline CD4+ count < 350/mm3 vs 4.2% women with baseline CD4+ > 350/mm3, P = 0.048)." (PMID 23894379, 2013). "Baseline CD4+ T cell count was not statistically associated with the incidence of severe liver toxicity among female Chinese patients, 29% (9/31) and 16% (10/63) in the patients with the baseline CD4+ T count >250/mm3, and ≤250/mm3, respectively (p = 0.184)." (PMID 22066007, 2011). "We did not observe a significant association between the development of hepatotoxicity and high CD4 cells count at NVP start, supporting the observation of low frequency of NVP induced liver toxicity in experienced patients." (PMID 30419834, 2018). "Other variables analyzed such as male gender, HIV transmission category, baseline CD4 count and baseline PVL were not statistically significantly associated with hepatotoxicity." (PMID 28222098, 2017). "The 24-month probability of occurrence of rash or hepatotoxicity was not different between women with a CD4 cell count >250 cells/mm3 and women with a CD4 cell count ≤250 cells/mm3 (8.3% vs. 9.9%, Log-rank test: p = 0.75)." (PMID 20576111, 2010).
inflammatory skin disease (11 papers, 2012 to 2025). Inflammatory skin disorders covers a broad category that includes many conditions ranging in severity, from mild itching to grave medical health complications These disorders are common in people of all ages and races. "AD is an inflammatory skin disease predominantly characterized by CD4+ T‐cell infiltrate in the lesional skin." (PMID 38488856, 2024). "T helper 2 (Th2)-mediated dermatoses are inflammatory skin diseases driven by CD4+ Th2 cells that produce interleukin (IL)-4, IL-5, IL-13, and IL-31, promoting immunoglobulin E (IgE) class switching, eosinophil recruitment, mast cell degranulation, and pruritus." (PMID 41226755, 2025). "It is known that CD4+ T helper (Th) cells play a pivotal role in inflammatory skin disorders." (PMID 37415985, 2023). "The major aim of the present study was therefore to study skin sections from a cohort of PV, BP and LP patients in order to investigate whether a similar polarized CD4+ T cellular signature could be identified in lesions of these inflammatory skin disorders." (PMID 37415985, 2023). "However, CD4 is also expressed by histiocytes and inflammatory T-lymphocytes, which can be abundant in this context and it must be kept in mind that CD4+ T lymphocytes also take place in inflammatory skin diseases." (PMID 35642346, 2023). "Human skin harbors a heterogeneous pool of immunocompetent cells, including DC subsets, Langerhans cells, CD4+, CD8+ T-cells, γδ T-cells, and innate lymphoid cells, that are able to produce pro-inflammatory cytokines/chemokines that can contribute to the pathogenesis of skin inflammatory disorders." (PMID 30972071, 2019).
IPEX syndrome (11 papers, 2011 to 2025). "This provides tantalizing evidence for the underlying mechanism for the increased %TSDR/CD4 in IPEX syndrome we have shown." (PMID 36600150, 2023). "Peripheral FOXP3 expression was normal (CD127−/CD4+/CD25+/FOXP3+—396 cells—63%) and a pathogenic mutation in FOXP3 gene (c.1150G>A; p.Ala384Thr), confirmed the diagnosis of IPEX syndrome." (PMID 36503523, 2022). "Ectopic expression of the FOXP3 gene in naive human CD4+ T cells from healthy donors or IPEX syndrome patients renders the cells suppressive." (PMID 29535721, 2018). "It has also been demonstrated that patients with IPEX syndrome who have missense mutations and deletions in splicing sites do not have Treg CD4+CD25+Foxp3+ lymphocytes and have a more severe form of the disease." (PMID 35207219, 2022). "IPEX syndrome is a congenital disorder of immune regulation caused by mutations in the FOXP3 gene, which is required for the suppressive function of naturally arising CD4 + CD25 + regulatory T cells." (PMID 22816667, 2012). "CD4+ T cells are thought to be at least partially responsible for AIE based on (a) the phenotypic similarities between AIE and the IPEX syndrome, (b) the role of CD4+ T cells in villous atrophy and (c) the aberrant CD4+ T cell subsets and CD4+ IEL reported in some cases of AIE." (PMID 22126605, 2011). "Additionally, the rare disorder of the immune system, immune dysregulation, polyendocrinopathy, enteropathy X-linked (IPEX) syndrome, is caused by mutations in the FOXP3 gene that result in defective development of CD4+ CD25+ Treg; children with IPEX syndrome demonstrate high levels of serum IgE." (PMID 23226205, 2012). "At the same time, the number of cells counted by other Treg surface markers (e.g., CD4( +), CD25( +), and CD127(low)) may no longer reflect fully functional Tregs which are highly variable in individuals with IPEX syndrome." (PMID 36600150, 2023).
kidney cancer (11 papers, 2019 to 2025). Primary or metastatic malignant neoplasm involving the kidney. "Myeloid cells (neutrophils and monocytes) constitute only one third of the infiltrating immune cells within the kidney cancer microenvironment, while half of all infiltrating immune cells are CD4 and CD8 T-cell lymphocytes." (PMID 40790491, 2025). "Infiltrating CD4+ T cells fascinate TGFβ1 expression and regulated kidney cancer cell proliferation by activating TGFβ1/YBX1/HIF2α signals." (PMID 35096961, 2021). "This increase was ascribed to elevated levels of both CD4highCD8low and CD4+CD8high subsets, except in kidney cancer where the increase in DP T cells was only attributed to the CD4highCD8low subset." (PMID 30984190, 2019). "Although KLRG-1+ CD4 T cells showed a higher frequency in tumors compared with blood from kidney cancer patients, they displayed similar frequencies in blood and tumors from patients with the remaining cancer types." (PMID 31709176, 2019). "Similarly, it was shown that CM prepared from the RENCA mouse kidney cancer cell line converted CD4+CD25- T lymphocytes into CD4+CD25+ Treg cells." (PMID 33916641, 2021). "NEIL3 showed a positive correlation with six types of immune cells in three cancer subgroups (pan-kidney cancer cohort (KIPAN, including KICH, KIRC, and KIRP), KIRC, and LIHC), involving B cells, CD8 T cells, CD4 T cells, DCs, macrophages, and neutrophils." (PMID 36612106, 2022). "Using flow-cytometry analysis, we identified CD4+CD8+ double positive (DP) T cells in peripheral blood mononuclear cells (PBMCs) from HD and from patients with bladder, prostate or kidney cancers." (PMID 30984190, 2019). "The pan-kidney cancer (KICH, KIRC and KIRP), LIHC and PRAD were clustered in to one sub-group featured with high proportion of T cells CD4 memory resting." (PMID 31074374, 2019). "Similarly, the proportion of CD3+, CD4+, and CD8+ T cells was lower in kidney cancer inoculated on AA-treated kidneys than that on PBS treated kidneys." (PMID 36470862, 2022). "Akkermansia muciniphila was correlated with increased immune cell infiltration in lung and kidney cancers, as CCR9+CXCR3+CD4+ T cells were recruited to the tumor bed in an interleukin-12-dependent manner and the ratio of CD4+ T cells to CD4+FoxP3+ T cells (Tregs) was increased." (PMID 34568308, 2021).
liver dysfunction (11 papers, 2018 to 2025). "This case highlights the need for clinicians to remain alert to the possibility of VBDS in HIV patients, particularly those with low CD4 counts and unexplained liver dysfunction." (PMID 41425512, 2025). "VBDS should be considered in HIV‐positive patients with unexplained liver dysfunction, particularly those with low CD4 counts." (PMID 41425512, 2025). "Patients with hepatopathy (OR=6.10, 95%CI=1.46-28.9), HIV viral load (OR=8.68, 95%CI=1.42-70.2; OR=19.4, 95%CI=3.09-179), operation time (OR=7.84, 95%CI=1.35-77.9), and CD4 count (OR=0.05, 95%CI=0.01-0.23) were risk factors for SSI (P-value < 0.05)." (PMID 37497209, 2023). "Spearman’s correlation analysis showed that Muribaculaceae, Akkermaniacaeae, [Eubacterium]_coprostanoligenes_group, RF39, Tannerellaceae have positive correlation with CD3+T, CD4+T and CD8+T cell counts while negatively correlated with liver dysfunction." (PMID 37201112, 2023). "Currently, the reduction of CD4 T cells and the naïve CD4 T-cell percentage are used in clinical practice as potential markers of complicated phenotype and of organ-specific complications, such as GLILD and hepatopathy." (PMID 40496855, 2025).
mantle cell lymphoma (11 papers, 2016 to 2025). Mantle cell lymphoma is a rare form of malignant non-Hodgkin lymphoma affecting B lymphocytes in the lymph nodes in a region called the ``mantle zone''. "In patients with mantle cell lymphoma in the relapsed or refractory setting, a combination of Venetoclax plus Ibrutinib shows efficacy, which was associated with expansion in CCR7-CD45RA+ CD8+ and CD4+ TEMRA with improved function." (PMID 34987640, 2022). "Notably peptides derived from the CDR3/FW3 region studied here were recently shown to be extensively presented on HLA class II in human mantle cell lymphoma B cells, and also recognized by idiotope-specific CD4+ T cells." (PMID 29038659, 2017). "Moreover, BMI-1 was shown to mediate the survival of memory CD4 T cells as well as mantle cell lymphoma cells via direct binding to the NOXA gene locus and repression of NOXA mRNA expression through histone modifications." (PMID 26935956, 2016). "Preclinical studies suggested that tumor cells in mantle cell lymphoma (MCL) can evade the immune antitumor response by several microenvironmental factors, including T cells which are able to inhibit cytokine CD4+CD25− production by interaction between PD-1 and PD-L1." (PMID 29850620, 2018).
medulloblastoma (11 papers, 2016 to 2026). A malignant, invasive embryonal neoplasm arising from the cerebellum. "In this study, we identified a significant association between CD4 T cells and favorable prognosis in medulloblastoma patients." (PMID 40575173, 2025). "Currently, the underlying anti-tumor mechanism of CD4 T cells in medulloblastoma remains undefined." (PMID 40575173, 2025). "Our findings offer valuable insights for therapeutic strategies, such as finding ways to increase the influx of beneficial CD4 T cells into the TME of medulloblastoma." (PMID 40575173, 2025). "Subsequently, we conducted a further analysis of the correlation between CD4 T cells and the prognosis of medulloblastoma molecular subgroups." (PMID 40575173, 2025). "In Pham CD’s study, a significant increase in CD4 T cells was observed in the medulloblastoma mouse models which were effective to anti-PD-1 treatment." (PMID 40575173, 2025). "The depletion of CDK5 in medulloblastoma xenograft model resulted in diminished PD-L1 expression and increased the numbers of CD4+ tumour-infiltrating lymphocytes, resulting in robust CD4+ T-cell-mediated tumour rejection." (PMID 31910742, 2020). "Specifically, DIPG, ATRT (TYR, MYC), and medulloblastoma (SHH) had increased levels of CD4 expression, also known to be expressed by human monocytes and macrophages, while CD8 expression tended to be decreased, except in the case of WNT-activated medulloblastoma." (PMID 41541220, 2026). "Our study demonstrated that the total T cells and CD4 T cells increased in the SHH subgroup, and an increase in CD4 T cells predicted a better 5-year PFS and OS in medulloblastoma." (PMID 40575173, 2025). "We found CD4 staining in eight samples (H-score > 0, 3 ATRTs, 3 ependymoma, 2 medulloblastoma), while other samples showed no CD4 staining." (PMID 37679810, 2023). "Besides, in a mouse model of spontaneous medulloblastoma, targeted STAT3 destruction of bone marrow cells altered the presence of CD4 + cell." (PMID 33101383, 2020). "The increase in CD4 T cells predicts a better prognosis in medulloblastoma patients, particularly within the SHH and non-WNT/non-SHH subgroups, and they may serve as a potential therapeutic target for medulloblastoma." (PMID 40575173, 2025). "The increase in CD4 T cells predicts a better prognosis in medulloblastoma patients, particularly within the SHH and non-WNT/non-SHH subgroups, and they might be taken as a therapeutic target for medulloblastoma." (PMID 40575173, 2025).
mumps (11 papers, 2012 to 2025). "Furthermore, cytotoxic/Th1-type CD4+ T cell responses against this epitope were found in a panel of mumps cases expressing other HLA-DR alleles." (PMID 30626672, 2019). "We recently isolated a MuV-specific CD4+ T cell clone by stimulating peripheral blood mononuclear cells (PBMCs) from a mumps case with the viral nucleoprotein (MuV-N)." (PMID 30626672, 2019). "In this study, we further explored the identity and relevance of the epitope recognized by the CD4+ T cell clone and ex vivo by T cells in a cohort of mumps cases." (PMID 30626672, 2019). "We recently isolated a MuV-specific CD4+ T cell clone, named MuTER.1, by stimulating PBMCs of a mumps case with the viral nucleoprotein (MuV-N)." (PMID 30626672, 2019). "Taken together, we identified the first naturally processed human MuV epitope that is broadly and strongly recognized in a HLA-DR-restricted manner by cytotoxic/Th1 type CD4+ T cells from persons recently infected with mumps." (PMID 30626672, 2019). "In this study, we identified the first MuV T cell epitope, which is derived from the viral nucleoprotein (MuV-N) and was recognized by a cytotoxic/Th1 CD4+ T cell clone that was isolated from a mumps case." (PMID 30626672, 2019). "Moreover, the epitope was predicted to bind a broad variety of common HLA-DRB1 alleles, which was confirmed by the epitope-specific cytotoxic/Th1 CD4+ T cell responses observed in multiple mumps cases with various HLA-DRB1 genotypes." (PMID 30626672, 2019). "Nineteen (17%) mumps patients were persons living with HIV infection, including 13 (68%) with CD4+ counts available within 18 months before onset of mumps symptoms; 12 (63%) persons had values ≥200 cells μL3." (PMID 32673295, 2020). "All four mumps patients expressing an HLA-DRB1*04 molecule showed a good CD4+ T cell response against the GTYR peptide, including the mumps case from which the clone was derived from (HLADRB1*04/1501)." (PMID 30626672, 2019).
oral lichen planus (11 papers, 2017 to 2023). Oral lichen planus is a chronic inflammatory oral condition of unknown aetiology characterized by T-cell-mediated chronic immune response and abnormal epithelial keratinization cycle. "MiR-29b was shown to interact with IFN-γ and induce DNA hypomethylation in CD4+ T cells of individuals with oral lichen planus." (PMID 35428200, 2022). "The FOXP3/miR-146a/NF-κB axis was previously reported to modulate the induction and function of CD4+ Treg cells to alleviate oral lichen planus." (PMID 34670484, 2021). "CD4+ cells had highest prevalence in the lamina propria of oral lichen planus (54.6%) compared with CHC (23.0%)." (PMID 31718115, 2019). "For example, miR-29b, which may be related to protein digestion and absorption pathways as well as focal adhesion pathways, has been reported to interact with IFN-γ and induce DNA hypomethylation in CD4+ T cells of individuals with oral lichen planus." (PMID 35428200, 2022). "Furthermore, they detected a positive miR-155- interferon-γ feedback loop in erosive oral lichen planus CD4+ cell samples which, according to these authors, may contribute to the immune re-sponse dominated by the Th1 type cells in this type of lesions." (PMID 28809371, 2017). "In the evaluation of CD3 + CD4+/CD3 + and CD3 + CD8+/CD3 + proportions, there was a higher percentage of these cells in the oral lichen planus group when compared with the oral lichenoid reaction group (p = 0.027 and p = 0.038 respectively)." (PMID 36397025, 2022). "Significant differences in proportions of CD4+ cells between tissue types occurred in the epithelium (p = 0.008), where these cells were more prevalent in CHC (3.2%) compared with both oral lichen planus (0.7%) and squamous papilloma (1.0%)." (PMID 31718115, 2019). "The FOXP3/miR-146a/NF-κB axis was previously reported to modulate the induction and function of CD4+ Treg cells to alleviate oral lichen planus, while other signaling pathways including microRNA-155-IFN-γ loop and FOXP3/miR-146a/TRAF6 pathways are involved in the pathogenesis of oral lichen planus." (PMID 34670484, 2021). "However, the proportion of CD3 + CD4+/CD3 + and CD3 + CD8/CD3 + cells is higher in the oral lichen planus group when compared with the oral lichenoid reaction group, suggesting that these cells may be important for the etiopathogenic mechanism of these lesions." (PMID 36397025, 2022).